THBS1 (thrombospondin 1)
Diseases named in the same sentence as THBS1 in open-access papers (continued):
Sharing a sentence is not in itself a finding about the gene and the disease.
tumor (continued). "The first member to be identified, THBS1, is an extracellular glycoprotein that plays multifunctional roles in the cell-matrix and cell-cell interactions, angiogenesis, and tumor progression." (PMID 32801999, 2020). "In the THBS family, THBS1 has been extensively researched, with diverse functions in tumor progress." (PMID 33244454, 2020). "The miR-17-92 cluster has previously been reported to amplify tumour angiogenesis in in vitro culture and mouse models, by repressing expression of anti-angiogenic proteins including thrombospondin-1 (THBS1) and connective tissue growth factor (CTGF)." (PMID 33182685, 2020). "Once produced by cancer cells, prosaposin acts in a paracrine and endocrine fashion inducing the expression of thrombospondin-1 in stromal cells at primary and distant tumor sites, which blocks neoangiogenesis and delays tumor growth." (PMID 33193295, 2020). "Thbs1 and Thbs2 have been well acknowledged as potent endogenous inhibitors of angiogenesis and tumor growth." (PMID 33154757, 2020). "In the MDA-MB-231 xenograft model, SFRP1 suppressed tumor growth by blocking the Wnt signaling and inhibited cancer cell adhesion and migration by blocking thrombospondin-1." (PMID 33007803, 2020). "In the context of distant metastasis in the endothelial niche, thrombospondin-1 was shown to induce sustained tumor quiescence, thereby inhibiting tumor expansion and spreading." (PMID 32014047, 2020). "The main mechanism by which CAFs promote the progression of CCA is to support the proliferation and survival of tumor cells through the expression of cytokines and growth factors, such as periostin, thrombospondin-1, SDF-1, MMP2, MMP9, and IL-1β." (PMID 32539768, 2020). "At least one way by which ECs counteract the growth of the neoplasm is mediated by TSP-1 (thrombospondin-1)." (PMID 33143050, 2020). "THBS-1 and -2 are another pair of targets with dysregulated expression involved in fibrosis, apoptosis of tumor cells and synthesis of DNA." (PMID 32225060, 2020). "As a matricellular glycoprotein, THBS1 regulates cellular phenotype and extracellular structure during tissue genesis and remodeling, and has been shown to regulate tumor progression and metastasis." (PMID 32894090, 2020). "LCM from SUM159 tumor-bearing mice contained 16 unique proteins relative to other LCM conditions, including the metastasis-associated proteins CCL7, FGFR4, GM-CSF, MMP3, thrombospondin-1 and VEGF." (PMID 31936750, 2020). "In this regard, Thymosin-ß4 (Tß4; TMSB4X) and THBS1 are considered as tumor promoters with a poor prognosis in different types of cancers." (PMID 32793473, 2020). "Western blot results showed that FN1(11/12),LTBP1(11/12), PLOD2(11/12), RCN3(10/12), THBS1(11/12) were increased in tumor tissues (Paired-samples t-test, p < 0.05), indicating that the screening results of TMT technology were credible." (PMID 32216815, 2020). "Increased expression of THBS1, an extracellular glycoprotein that has multiple roles in cell-matrix and intercellular interactions, significantly correlated with tumor differentiation." (PMID 33178597, 2020). "Because miRNAs can act either as tumor suppressors or oncogenes, depending on their target genes in different recipient cells, we identified three anti-angiogenesis genes (THBS1, STAT1, LIF) as target gene of miR-194." (PMID 31700002, 2019). "Over-expression of THBS1 in the T-cell compartment inhibits angiogenesis, thereby restraining tumor growth." (PMID 31847842, 2019). "In vivo, mouse survival was increased in animals xenografted with U87 THBS1-knockdown tumours when treated with anti-angiogenic therapy." (PMID 30850588, 2019). "Contra-lateral invasion was significantly decreased by more than 49% for P3 THBS1-1 shRNA tumours and 76% for P3 THBS1-2 shRNA tumours in comparison with shRNA control tumours." (PMID 30850588, 2019).
tumor (continued). "The significance of the role of THBS1 is supported by an independent laser-capture microdissection and qPCR analysis, which showed increase of THBS1 mRNA in the invasive area when compared to the tumour core." (PMID 30850588, 2019). "BZRAP1-AS1 negatively regulated THBS1 through inducing methylation, thus promoting tumor angiogenesis." (PMID 31847842, 2019). "THBS1 silencing inhibits tumour cell invasion and growth, alone and in combination with anti-angiogenic therapy." (PMID 30850588, 2019). "We have previously shown that THBS1 is expressed in tumour blood vessels and in specific patient-derived xenograft (PDX) models." (PMID 30850588, 2019). "In contrast, THBS1 is an ECM glycoprotein that inhibits tumor cell growth and metastasis partly due to its anti-angiogenic effect." (PMID 31341222, 2019). "THBS1 was detected in both, tumour vessels and tumour cells, the latter being enhanced in the peripheral invasive areas (margin)." (PMID 30850588, 2019). "According to The Cancer Genome Atlas (TCGA), THBS1 expression is found to be increased in GBMs when compared to grade II and III tumours, and linked to patient survival." (PMID 30850588, 2019). "Taken together, these data indicate that silencing of BZRAP1-AS1 can suppress tumor angiogenesis in vivo through up-regulation of THBS1." (PMID 31847842, 2019). "We have previously shown that THBS1 is expressed in tumour blood vessels and in specific PDX models." (PMID 30850588, 2019). "It seems possible that these results are due to multifaceted and sometimes opposing effects of THBS1 on tumor progression depending on the molecular and cellular composition of the microenvironment." (PMID 31412643, 2019). "This was further confirmed by laser-capture microdissection and qPCR analysis where THBS1 mRNA was found significantly increased in the invasive area when compared with the tumour centre." (PMID 30850588, 2019). "The results demonstrated that the tumor volume and weight of mice were decreased by over-expression of THBS1 or silencing of BZRAP1-AS1 (p < 0.05)." (PMID 31847842, 2019). "Survival was significantly increased for mice implanted with P3 tumours transduced with either one of the THBS1 shRNA constructs." (PMID 30850588, 2019). "RNA sequencing of patient-derived xenograft tissue from laser capture micro-dissected peripheral and central tumour areas demonstrates that THBS1 is one of the gene with the highest connectivity at the tumour borders." (PMID 30850588, 2019). "Three possible biomarkers associated with CNS metastases in TNBC tumours were identified: ISG15, THBS1 and AP1M1." (PMID 30792808, 2019). "In bevacizumab-treated P3 tumours, an increase in THBS1 expression was seen in the tumour core by western blot." (PMID 30850588, 2019). "Tumour Thrombospondin-1 (THBS1), Annexin II (ANXA2) and PDGFB were found to have the highest connectivity with genes of the stromal compartment." (PMID 30850588, 2019). "Depend on its role to suppress angiogenesis, THBS1 was shown to retard tumour growth and is often found down-regulated in tumour samples." (PMID 30922331, 2019). "The most strongly affected by the modified Wnt microenvironment is the up-regulated THBS1, that is a secreted glycoprotein involved in wound healing, angiogenesis and inflammatory response as well as in inhibition of tumor growth." (PMID 31492143, 2019). "When patient GBM tumour samples from multiple areas were analysed by IHC, a specific pattern of THBS1 staining was seen in the central tumour area and at the location of invasive cells." (PMID 30850588, 2019). "It has recently been shown that TAX2, a 12 amino-acid peptide stretch of CD47, specifically inhibits the THBS1/CD47 interaction, causing necrosis in various tumour models." (PMID 30850588, 2019).
tumor (continued). "This is also consistent with the results obtained with the P3 tumour model where THBS1-knock down in combination with bevacizumab treatment led to a marked inhibition of both in vitro and in vivo invasion, with a significant impact on mouse survival." (PMID 30850588, 2019). "Thrombospondin-1 is a large glycoprotein secreted by platelets and synthesized by many cell types, including endothelial and tumor cells." (PMID 29855483, 2018). "THBS1, much like PEDF, has been implicated as a protein with dual anti-tumor and anti-angiogenic activity." (PMID 29464047, 2018). "THBS1 was the first member to be identified in the thrombospondins family and is a main player in the tumour microenvironment." (PMID 30055645, 2018). "Due to its essential role in tumour progression, THBS1 represents a perspective therapeutic target in cancer treatment." (PMID 30055645, 2018). "In BETi-sensitive CRC cells, JQ1 also impaired tumor angiogenesis through the c-myc/miR-17-92/CTGF+THBS1 axis." (PMID 29472532, 2018). "The observed relationship between THBS1 and membrane vesicle aparatus in angiogenic tumor types provides mechanistic insight into the finding of EV-associated THBS1." (PMID 29221141, 2017). "We now show new data indicating that anti-estrogen therapy regulates CD47 expression and implicates its ligand, thrombospondin-1, in regulation of tumor macrophage infiltration." (PMID 28815041, 2017). "THBS1 is a multifunctional glycoprotein found to be overexpressed in the tumor microenvironment, where it regulates tumor cell adhesion and migration, metastasis and angiogenesis." (PMID 29221141, 2017). "Thrombospondin I (THBS1) is an endogenous inhibitor of angiogenesis, which limits blood vessel density in normal tissues and curtails tumor growth." (PMID 29113313, 2017). "Together, these data demonstrated that multiple KSHV miRNAs are really involved in dhC16-Cer up-regulation of THBS1 from PEL cells and causing tumor cell cycle arrest." (PMID 28146424, 2017). "BIRC3, CAV1, CAV2, FN1, ITGA1 and THBS1 were functionally enriched to focal adhesion, which contributes to antiangiogenic and anti-tumour effects." (PMID 27557147, 2016). "One prominent example, oncogenic miR-17-92 family, is known to stimulate angiogenesis in the adjacent tumor endothelium by direct repression of the secreted, antiangiogenic molecules thrombospondin-1 (TSP-1) and connective tissue growth factor (CTGF)." (PMID 27191983, 2016). "ApcMin/+:Thbs1−/− mice exhibited decreased survival and higher tumor multiplicities in the small and large intestine relative to ApcMin/+ mice when fed a low (5%) fat western diet." (PMID 27239962, 2016). "Tumor cell proliferation rates in the endothelial niches were correlated with their Tie2 receptor activities and thrombospondin-1 (TSP-1) levels." (PMID 27353038, 2016). "CAV1 and CAV2 were correlated with tumour growth and metastasis, and FN1 was a potential biomarker for some cancers, while ITGA1 and THBS1 were also associated with cancer risk." (PMID 27557147, 2016). "While TGFB1 was induced in the tumour, its activators integrins and THBS1 were upregulated in both cell types, highlighting the reciprocal crosstalk between the two cell types to regulate cell adaptation and tissue remodeling." (PMID 27049916, 2016). "The role of THBS1 in tumour growth and metastasis is complicated by its controversial function as a cancer inhibitor or promoter." (PMID 25652121, 2015). "Thrombospondin-1 is considered a main actor within a tumor microenvironment, while it exerts intricate and sometimes opposite effects on tumor progression." (PMID 26578962, 2015).
tumor (continued). "Thrombospondin-1 (TSP-1) is a large matricellular glycoprotein known to be overexpressed within tumor stroma in several cancer types." (PMID 26578962, 2015). "Thrombospondin-1 has long been considered to play a role in tumor progression; several studies carried out 20 years ago found it to be overexpressed within tumor stroma and in high circulating levels in several cancers." (PMID 26578962, 2015). "Of the 9 genes tested, 8 (THBS1, CYR61, CTGF, MXRA5, SPP1, LTBP2, TGFBR1 and COL11A1) were found by qRT-PCR to be significantly differentially expressed in tumor-associated fibroblasts, for a validation rate of 89%." (PMID 26575166, 2015). "Hypermethylation was associated with advanced tumor grade for BRCA1 (P = 0.003), CDH1 (P = 0.002), HSPA2 (P = 0.009), RASSF1A (P = 0.017), and THBS1 (P = 0.000), while methylated GDF15 (P = 0.002) promoter was associated with low tumor grade." (PMID 25613404, 2015). "let-7 family member miRNAs have been shown to be pro-angiogenic and to promote tumour angiogenesis by inhibiting the anti-angiogenic factors thrombospondin-1 (TSP-1) and tissue inhibitor of metalloproteinase-1 (TIMP-1)." (PMID 24886719, 2014). "In our studies THBS1 expression in LRC was associated with an EMT-like phenotype and potentially implicates TGF-beta pathway activation in LRC to mediate tumor progression." (PMID 25051363, 2014). "Host defenses that inhibit tumor angiogenesis include the endogenous angiogenesis inhibitors thrombospondin-1 and endostatin, which counteract the effects of pro-angiogenic factors." (PMID 24465581, 2014). "Several extrinsic factors previously reported to be associated with the tumor microenvironment were identified, including GCSF, THBS1, S100A8/A9, CCL2, TNF and TNFSF11." (PMID 25593989, 2014). "Thrombospondin 1 (THBS1) was the first member to be identified, and has been shown to modulate tumor progression and metastasis." (PMID 25051363, 2014). "Thrombospondin (THBS1) is an antiangiogenic extracellular matrix protein that inhibits tumour growth and metastasis in animals." (PMID 24229053, 2013). "THBS-1 has proven to reduce degradation of uPA by preventing association of uPA, uPAR and PAI-1, resulting in increased migration of tumor cells." (PMID 24223867, 2013). "Although there is no consensus of its clinical relevance, there is a trend towards an inverse correlation between increased THBS1 expression in tumour stroma (evaluated as stromal area) or stromal cells and nodal positivity." (PMID 24229053, 2013). "Physiologically, THBS-1 is secreted by platelets; however, a number of other cells including smooth muscle cells, astrocytes, endothelial cells and various tumor cells are also able to produce THBS-1." (PMID 24223867, 2013). "The miR-17-92 cluster contains miR-18a and miR-19a that have been shown to affect tumor angiogenesis by downregulating the mRNA expression of THBS1 and CTGF genes, respectively." (PMID 22383169, 2012). "PPARα knockout monocyte/macrophages exist in a highly inflammatory state producing large amounts of thrombospondin-1 and inhibiting tumor growth." (PMID 22028915, 2011). "Elevated THBS1 expression in MDSCs of 4T1 tumor host seems contradictory to the metastasis phenotype of aggressive tumor cells." (PMID 21853032, 2011). "Aside from the inhibitory activity of angiogenesis, THBS1 also suppresses tumor growth by activating transforming growth factor beta and affects tumor cell function through interaction with cell surface receptors and regulation of extracellular proteases." (PMID 19463170, 2009). "HDACi are reported to be potent inhibitors of tumor angiogenesis and induction of THBS1 has previously been reported following HDAC inhibition." (PMID 19948057, 2009). "Key molecules investigated in ageing and in tumour biology include thrombospondin 1 (TSP1) and secreted protein acidic and rich in cystein (SPARC)." (PMID 18182993, 2008).
tumor (continued). "Here we show that PPARα deficiency in the host leads to overt inflammation that suppresses angiogenesis via excess production of the endogenous angiogenesis inhibitor thrombospondin-1 and prevents tumor growth." (PMID 17327920, 2007). "The role of THBS1, the most widely studied gene in this family, in angiogenesis and tumor progression remains controversial." (PMID 17022822, 2006). "An intriguing subset of genes in the cornea signature has been studied in tumor metastasis models because these genes encode proteins that regulate cell-cell or cell-matrix interactions (TWIST, MMP10, SERPINB5, THBS1, CEACAM1, C4.4A)." (PMID 16168081, 2005). "Thrombospondin-1 expression in the tumour stroma was found in 34% of ID1 strong cases, compared with 57% in ID1 weak cases (χ2 test, P=0.014)." (PMID 16189525, 2005). "We have previously shown that platelet-produced thrombospondin-1 up-regulates the urokinase plasminogen activator and its receptor and promotes tumour cell invasion." (PMID 10917542, 2000). "Although tumour cells produce thrombospondin-1 in vivo, they produce only minimal amounts of thrombospondin-1 in vitro." (PMID 10917542, 2000). "m6A-modulated mRNA stability, particularly via IGF2BP1, regulates the expression of RRM2 and thrombospondin 1 (THBS1), contributing to resistance against ferroptosis and the glycolytic reprogramming of tumor-associated macrophages, ultimately promoting tumor progression and fibrosis." (PMID 41376856, 2026). "Moreover, extracellular matrix (ECM) proteins, such as thrombospondin-1 (TSP-1), and the balance between proteases and their inhibitors have also been implicated in tumor progression, metastasis, and response to therapy." (PMID 40940829, 2025). "The TGF‐βpathway genes (THBS1 and SMAD2) report on epithelial–mesenchymal transition and immunosuppressive signaling, while Th2‐associated markers (CCR4, GATA3) indicate a helper T‐cell polarization state that favors tumor progression." (PMID 41407509, 2025). "Compared with untreated controls, tumour-bearing mice treated with navarixin—an orally bioavailable small-molecule antagonist of CXCR1/2—or with thrombospondin-1 (TSP-1), which simultaneously blocks CD47 on tumour cells and CD36 on macrophages, presented significantly reduced tumour volumes." (PMID 41163221, 2025). "Moreover, its interaction with immune cells and its role in modulating the tumor microenvironment highlight THBS1 as a key player in the complex interplay between cancer cells and the host immune system." (PMID 41019041, 2025). "Additionally, scratch wound healing assays demonstrated that overexpression of THBS1 significantly enhanced the migratory capacity of tumor cells, whereas its suppression had the converse effect, impeding cell migration." (PMID 41019041, 2025). "Tumor macrophages demonstrated significant upregulation of genes associated with polarization to the tumorigenic and immunosuppressive M2 phenotype (e.g., APOE, CD163, WNT5A, and THBS1)." (PMID 40848148, 2025). "Previously, THBS1 was reported to be an inhibitor of angiogenesis and tumor progression." (PMID 40083708, 2025). "THBS1 is involved in various physiological and pathological processes, including tumor development, fibrosis, angiogenesis, cell migration, and proliferation, and may influence necroptosis through its interaction with TAK1." (PMID 41021615, 2025). "Moreover, CD47 promotes tumor progression in various malignancies by interacting with thrombospondin-1 (TSP-1)." (PMID 40732268, 2025). "Additionally, we found other abundant proteins in PDAC samples implicated in cytoskeletal dynamics, cell motility and tumor progression such as TUBB4A, SEPTIN7, ARHGDIA, THBS1, and PPP1R12A, similar to reports from the literature." (PMID 41007761, 2025). "Additionally, the cathepsin C-PR3-IL-1β axis stimulates p38 phosphorylation and ROS production in neutrophils, leading to NET formation, which degrades thrombospondin-1 and supports tumor cell growth in the lungs." (PMID 41303697, 2025).